LUM (lumican)
Diseases named in the same sentence as LUM in open-access papers (continued):
Sharing a sentence is not in itself a finding about the gene and the disease.
breast carcinoma (continued). "Troup and colleagues found that a greater number of ER-positive tumors (n = 99) compared with ER-negative tumors (n = 6) had lumican protein expression ≥ 25th percentile among 140 women with breast cancer (P = 0.002)." (PMID 19036156, 2008). "Besides, LUM exhibits antitumor effects in lung cancer, breast cancer and pancreatic ductal adenocarcinoma." (PMID 37692065, 2023). "The overall prognostic tendency of LUM in breast cancer was a risk factor, although the results were not statistically different." (PMID 37692065, 2023). "A literature search of parallel systems revealed that in breast cancer, high stromal-cell expression of LUM adjacent to the tumor stalls tumor growth, and lowered stromal expression of LUM correlates with higher breast cancer mortality rates and increased severity." (PMID 36873459, 2022). "LUM may block or even revert the many metastatic characteristics that EMT confers to breast cancer cells." (PMID 36510567, 2022). "In contrast, lumican has previously been shown to inhibit breast cancer migration." (PMID 34885059, 2021). "Likewise, in breast cancer, lumican significantly downregulates the migratory abilities of tumor cells in a mannerdependent on their hormone receptor status." (PMID 34572532, 2021). "In breast cancer, high expression of LUM indicates poor prognosis." (PMID 32319226, 2020). "The obtained data regarding the effects of lumican on breast cancer cell morphology generated the question whether the EMT program was affected by such treatment." (PMID 28332606, 2017). "Interestingly, high level of lumican expression in breast cancer tissue was shown to be correlated with low level of expression of ER in the tumour." (PMID 28332606, 2017). "Therefore, the effect of lumican on cell morphology of these two types of breast cancer cells was also evaluated." (PMID 28332606, 2017). "Thus, along with others, we used an RNA microarray to detect the expression of many ECM molecules in ovarian and breast cancer cell lines, and one of these molecules was LUM." (PMID 29088800, 2017). "In both cases, lumican effect on EMT/MET transition of breast carcinoma cells might be partly explained by an endocytosis mechanism either of lumican, ER or by an alteration of their expression." (PMID 28332606, 2017). "Moreover, lumican achieved a striking decrease of the proteolytic activity of MMP-14 both in the highly-invasive MCF-7/SP10+ and in the aggressive MDA-MB-231 cells, rendering lumican as a critical inhibitor of breast cancer invasion and metastasis." (PMID 28332606, 2017). "Furthermore, shERβMDA-MB-231 breast cancer cells treated with lumican exhibited reduced proteolytic activity of MMP-14 and expression levels of MMP-7." (PMID 28332606, 2017). "Expression of the proteoglycans lumican and decorin has been found to be increased in stromal tissue associated with breast cancer and, in the absence of cancer, in women with extensive mammographic density." (PMID 25010427, 2014). "We hypothesized that genetic variation in the decorin (DCN) and lumican (LUM) genes may contribute to breast cancer." (PMID 19036156, 2008). "Associations with breast cancer risk for the DCN and LUM genes were observed with haplotype analyses in the Mayo Clinic sample." (PMID 19036156, 2008). "Two copies of the minor allele in LUM rs2268578 were associated with an average 60% increased risk of breast cancer compared with women with no copies, and the data suggest increased risk for ER-positive tumors." (PMID 19036156, 2008). "Lumican is not expressed in cancer cells in breast cancers but in fibroblasts, and it is associated with high tumour grade, low ER levels and young age." (PMID 17555561, 2007). "LUM has been shown to be associated with HSP90 and a lack of LUM expressions in human breast cancer may limit the clinical efficacies of HSP90 inhibitors." (PMID 37692065, 2023).
breast carcinoma (continued). "Based on the analysis of scRNA-seq and bulk RNA-seq data, we built and validated a cancer fibroblast-related risk signature consisting of five genes (BGN, LUM, CCL19, CEBPD, and ID3) that may be utilized as an independent prognostic indicator for breast cancer patients." (PMID 36510567, 2022). "Thus, as lumican may attenuate or even annulate specific EMT-correlated metastatic features in breast cancer cells, a lumican-based anticancer therapy targeting EMT could be beneficial." (PMID 34572532, 2021). "The obtained data suggest that the treatment with lumican may be beneficial for the breast cancers and further studies on the mechanisms and particularly on the cell signalling affected in relation to the ER status will improve our understanding on the pathways affected." (PMID 28332606, 2017). "The weaker association of LUM rs2268578 with breast cancer risk in the SEARCH sample may be due to a lack of causal association of this SNP with breast cancer, or the results may be a more valid estimate of effect." (PMID 19036156, 2008). "Disease-specific survival discrepancy was observed comparing breast cancer patients of the upper and lower quartile of the collagen family (COL2A1, COL11A1, COL6A1, COL6A2), THBS1 and LUM gene expression signature (log-rank test, P = 0.06)." (PMID 40927672, 2025). "According to the xiantao database, COL1A2, COL3A1, FGA, LUM, APOA1, APOH, and COL5A2 were more highly expressed in breast cancer than in normal tissues (p < 0.05), while the opposite pattern was seen for ALB and FBN1 (p < 0.05)." (PMID 37079213, 2023). "Lumican downregulates integrin signaling (FAK, Erk1/2, AKT) and inhibits EMT and the formation of lamellipodia in breast cancer cells." (PMID 34282767, 2021). "In this study, we evaluated the effects of lumican in the expression of matrix effectors, cell morphology and functional properties of MCF-7/SP10+ vs MCF-7/c and shERβMDA-MB-231 vs MDA-MB-231 breast cancer cells." (PMID 28332606, 2017). "Our observations advocate that the lumican-induced suppression of the expression of MMPs, and mostly of MMP-14, comes in agreement with its inhibitory effect in breast cancer cells migration." (PMID 28332606, 2017). "In order to evaluate the effect of lumican in the basal functional properties of MCF-7/c and MCF-7/SP10+ breast cancer cells, cell proliferation, migration and invasion assays were conducted." (PMID 28332606, 2017). "First, we evaluated the effect of lumican treatment on cell morphology of MCF-7/c and MCF-7/SP10+ breast cancer cells." (PMID 28332606, 2017). "Furthermore, it remains possible that the other variants in DCN and LUM that were not selected for genotyping in SEARCH may also influence breast cancer risk." (PMID 19036156, 2008). "Compared with women with no copies of the minor allele in LUM rs2268578, women with two copies showed the greatest risk for breast cancer in both the Mayo Clinic sample (OR = 2.2, 95% CI = 1.1 to 4.3; P2 df = 0.002) and the SEARCH study sample (OR = 1.4, 95% CI = 1.0 to 2.1; P2 df = 0.13)." (PMID 19036156, 2008). "In breast cancer, lumican may inhibit or even reverse the process of EMT and lumican-based therapy might be feasible." (PMID 40927672, 2025). "It was found that OV patients with elevated LUM levels were not sensitive to chemotherapy, while breast cancer, colorectal cancer and GBM patients with elevated LUM levels had greater chemotherapeutic benefits, relative to those with low expressions." (PMID 37692065, 2023). "LUM mRNA is specifically expressed in breast cancer tissues but not in normal breast tissues, suggesting that LUM is differentially expressed during breast tumor progression." (PMID 36510567, 2022). "Therefore, we evaluated the effect of lumican on the expression profiles of major ECM components, in MCF-7/c and MCF-7/SP10+ breast cancer cells." (PMID 28332606, 2017).
breast carcinoma (continued). "The cytoskeleton formation of MCF-7/c breast cancer cells was not significantly affected by lumican treatment, as shown by F-actin staining." (PMID 28332606, 2017). "Our data point to the conversion of established EMT status of the aggressive breast cancer cells MCF-7/SP10+ and MDA-MB-231 into a more epithelial-like state, triggered by the treatment of cells with lumican and the knockdown of ERα and the suppression of ERβ, respectively." (PMID 28332606, 2017). "Another important member of the SLRP family, lumican, is specifically expressed in breast cancer tissues, but not in normal breast tissues." (PMID 25140302, 2014). "Moreover, lumican decreased the expression levels of the mesenchymal markers slug/snail-2 zeb1, vimentin and fibronectin and the epithelial marker E-cadherin in MDA-MB-231 breast cancer cells." (PMID 28332606, 2017).
pancreatic cancer (28 papers, 2014 to 2025). "Furthermore, LUM mRNA overexpression is associated with higher tumor grade, invasion and stage in breast and pancreatic cancers." (PMID 34590603, 2021). "That is the case for Lumican expression by pancreatic cancer cells, which need it to proliferate, while Lumican secreted by stromal cells has been shown to enhance apoptosis of this type of tumor cells." (PMID 39796053, 2024). "Other cancer cell types that have been studied regarding the lumican-dependent motility effects include lung, breast, colon, liver, bladder, and pancreatic cancer, as well as neuroblastomas." (PMID 34572532, 2021). "In combination with lumican, gelsolin displays high accuracy in distinguishing pancreatic cancer from chronic pancreatitis (95% specificity)." (PMID 34947825, 2021). "In pancreatic cancer, the expression of lumican was demonstrated by a immunohistological analysis, where pancreatic stellate cells were identified as a major source of this PG." (PMID 34572532, 2021). "On the other hand, it was shown that lumican enhanced the adhesion and migration on the collagen of both pancreatic cancer cells and pancreatic stellate cells in a manner dependent on TGF-Β." (PMID 34572532, 2021). "The expression of lumican in stromal tissues is correlated with shorter survival times of pancreatic cancer patients." (PMID 34885059, 2021). "In pancreatic cancer, lumican is specifically localized in alpha cells of islets, acinar cells, collagen fibrils, fibroblasts close to pancreatic cancer cells, and cancer cells." (PMID 31406961, 2019). "On the contrary, lumican overexpression within the pancreatic cancer TME in vivo produced uniformly smaller tumors, correlated with reduced vascular density, enhanced Fas-mediated endothelial apoptosis, and reduced angiogenesis in TME24,25." (PMID 31406961, 2019). "It has previously been reported that the localization of lumican in the stromal tissue correlates with advanced-stage pancreatic cancer, retroperitoneal and duodenal invasion, and tends to correlate with shorter survival." (PMID 31406961, 2019). "LUM has been reported to correlate with an advanced stage of pancreatic cancer and with migration and invasive potential in gastric, colon and bladder cancer." (PMID 31861249, 2019). "The expression of LUM in stromal tissues correlated with shorter survival times of pancreatic cancer patients." (PMID 29088800, 2017). "This form was also the most abundant form of LUM in cell lysates from the MIA PaCa-2 pancreatic cancer cell line." (PMID 29088800, 2017). "TGF-β1 and CM from pancreatic cancer cells synergistically suppressed decorin and lumican, and stimulated versican expression in pancreatic stellate cells." (PMID 25593993, 2014). "Lumican is also identified as a marker protein in pancreatic cancer and plays an integral role in the development and progression of both gastrointestinal and non‐gastrointestinal tumours, including liver, gastric, colorectal, lung, breast and prostate cancers." (PMID 40537154, 2025). "When secreted by stromal cells, Lumican enhanced the apoptosis of pancreatic cancer cells." (PMID 39796053, 2024). "In addition to its protumourogenic properties, LUM also has been reported to inhibit tumour development and suppress pancreatic cancer cell growth by stimulating the growth of pancreatic cells and inhibition of tumour cell migration." (PMID 38474072, 2024). "Moreover, LUM protein levels are highly elevated in gastric cancer, colon cancer and pancreatic cancer." (PMID 37692065, 2023). "In a separate cancer model, lumican secreted by stromal cells was shown to attenuate the expression and activity of hypoxia-inducible factor-1α (HIF1α)via Akt signaling, leading to the enhanced apoptosis of pancreatic cancer cells." (PMID 34572532, 2021).
pancreatic cancer (continued). "Lumican (LUM) is one of the type II SLRPs, and its expression is significantly increased in a variety of tumors, especially lung cancer, gastric cancer, colon cancer, pancreatic cancer and bladder cancer." (PMID 34888227, 2021). "Furthermore, lumican was determined to trigger, characterized with apoptosis, a quiescent pancreatic cancer state." (PMID 34572532, 2021). "In the context of pancreatic cancer, stromal lumican is primarily secreted from pancreatic stellate cells and exerts an anti-tumor effect where high stromal levels of lumican are closely associated with decreased recurrence and increased survival following surgical resection." (PMID 33020183, 2020). "Similarly, lumican overexpression in pancreatic cancer increased cell invasiveness and proliferation." (PMID 32548117, 2020). "Importantly, serum gelsolin, particularly together with lumican, was proposed as a highly sensitive combined biomarker for distinguishing pancreatic cancer and pancreatitis (at 95% specificity gelsolin-lumican reached 80% sensitivity)." (PMID 30149613, 2018). "Because the N-glycosylated form of LUM was reported previously in pancreatic cancer, we checked whether PGNase F digestion could decrease the molecular mass of LUM." (PMID 29088800, 2017). "In pancreatic cancer, the expression of LUM was observed both in cancer cells as well as in stroma." (PMID 29088800, 2017). "Another study identified the lumican/EGFR/AKT/HIF1 α signaling pathway as a mechanism to inhibit pancreatic cancer cell survival and proliferation and prolonged survival after tumor resection, which stressed that lumican plays a restrictive role in EGFR-expressing pancreatic cancer progression." (PMID 27399694, 2016). "However, LUM is expressed in high-grade pancreatic cancers with a low degree of differentiation and in GBM patients, as well." (PMID 26230845, 2015). "Indeed, lumican has been reported to regulate cell migration in prostate and colorectal cancer, where is also related to a worse prognosis, and tumor progression in pancreatic cancer." (PMID 25961303, 2015). "LUM also inhibits cell adhesion and promotes the migration of osteosarcoma cells by regulating the transforming growth factor β2 (TGF-β2)/SMAD2 pathway, and a 70-kDa LUM proteoglycan seems to enhance cancer cell proliferation and inhibits the migration of pancreatic cancer cells." (PMID 26230845, 2015). "Their results showed that gelsolin, lumican, and tissue inhibitor of metalloproteinase 1 have better area under curve (AUC) values than CA19-9 to discriminate pancreatic cancer from healthy controls and chronic pancreatitis controls." (PMID 33672926, 2021). "Given the low efficacy of chemotherapeutics against pancreatic cancer, data revealing potent cytotoxicity in PDAC via lumican and gemcitabine co-treatment posit lumican as a promising ECM-derived protein therapy to sensitize cancer cells to chemotherapeutics." (PMID 33020183, 2020). "Additional supplementation with lumican suppressed cell growth by binding to EGFR and, subsequently, blocked downstream pathways in pancreatic cancer." (PMID 32825245, 2020). "The aim of this mini-review is to summarize our recent publication that hypoxia reduces stromal lumican in PDAC through autophagy-mediated degradation and reduction in protein synthesis within pancreatic cancer stellate cells." (PMID 31406961, 2019). "Three of the 5 candidate proteins, including GSN, lumican (LUM; a member of the SLRP family), and TIMP1, demonstrated an AUC value above 0.75 in differentiating pancreatic cancer from the controls." (PMID 24708694, 2014). "Moreover, secreted 70-kDa lumican by PDAC cells stimulated growth and inhibited invasion of human pancreatic cancer." (PMID 31406961, 2019).
pancreatic cancer (continued). "In conclusion, these recent findings by our group provide important new insights to build and deepen our understanding of the molecular interactions between stromal lumican and the TME and provide a rationale to design credible antitumor approaches against pancreatic cancer." (PMID 31406961, 2019).